ALDH1A3 (aldehyde dehydrogenase 1 family member A3)
Diseases named in the same sentence as ALDH1A3 in open-access papers (continued):
Sharing a sentence is not in itself a finding about the gene and the disease.
cancer (continued). "Dissecting the role of ALDH1A3 isoform in MPM cells and tumour microenvironment can open new fronts in the treatment of this cancer." (PMID 37047661, 2023). "Three X-ray structures are presented of human aldehyde dehydrogenase family 1 member A3 (ALDH1A3), a potential cancer stem cell biomarker (alone, with NAD+ and with ATP) and structure determination performed using molecular replacement." (PMID 35418200, 2022). "With these results, we demonstrate that ALDH1A3 inhibitor NR6 is able not only to interfere with cell growth, but also with the migratory and invasive potential of U87MG and HCT116 cancer cell lines." (PMID 33478031, 2021). "Several isoforms of the ALDH1 family (ALDH1A1, ALDH1A2, ALDH1A3, ALDH1B1, ALDH1L1, and ALDH1L2) are used as cancer stem cell markers in a variety of cancers." (PMID 34680942, 2021). "Different isoforms of the ALDH1 subfamily have been commonly described as biomarkers for CSCs in several cancer cell types, where both ALDH1A1 and ALDH1A3 are highly expressed in stem-cell-like subpopulations of different cancer types." (PMID 34641313, 2021). "Of these, ALDH1A3, TM4SF1, and PROM1 were identified as cancer stem cell markers and CAV1 was EMT‐related." (PMID 31498560, 2019). "In accordance with the results of cancer cell analysis, this experiment revealed diminished expression of AKR1C1 (FC=1.6-2.4) and ALDH1A1 mRNAs (FC=1.7), as well as upregulation of ALDH1A3 mRNA in xenograft tumors (FC=1.7-4.0)." (PMID 31413744, 2019). "Signal transduction genes (i.e., ADCY4/7/8/9,) are also in the list of our 102 genes, which also includes cancer stem cell signaling genes (i.e., WNT7A, GLI1/2/3, NOTCH2/3/4, ALDH1A3)." (PMID 29304754, 2018). "Elevated activity of additional ALDH isoforms, namely ALDH1A2, ALDH1A3, ALDH1A7, ALDH2*2, ALDH3A1, ALDH4A1, ALDH5A1, ALDH6, and ALDH9A1, has been observed in normal and cancer stem cells." (PMID 30087899, 2018). "Together, these findings ascribe a novel function for ALDH1A3 in an aggressive GSC phenotype via the up-regulation of tTG, and suggest the potential for a similar role by ALDH1 family members across cancer types." (PMID 28423611, 2017). "TM4SF4 knockdown weakened sphere forming and suppressed the expression of cancer stem cell markers such as ALDH1A1, ALDH1A3, Oct3/4, Sox2." (PMID 29254164, 2017). "Prognostic data on the ALDH1 in various cancers have been accumulated predominantly by using IHC of paraffin embedded cancer tissues with isotype-specific antibodies, ALDH1A1 or ALDH1A3." (PMID 26783961, 2016). "RT-qPCR was used to quantify the expression of TROP2 mRNA as well as that of putative markers for basal/cancer stem cells (CD49f, POU5F1 (Oct4), DCLK1, ALDH1A3) or luminal stem cells (NKX3.1) in residual tumors." (PMID 27283984, 2016). "They found that ALDH1A3 expression correlated better with ALDH1 activity and with tumor grade, metastasis and cancer stage." (PMID 22280212, 2012). "MBE1 was next screened for nonspecific cytotoxicity in ALDH1A3+ cancer cells (MDA-MB-468) and normal human fibroblastic cells (HaCaT) as compared to other reported ALDH1A inhibitors." (PMID 41210994, 2025). "ALDH1A3 expression is largely absent in syngeneic mouse tumor lines as compared to its broader expression in human cancers." (PMID 41210994, 2025). "Taken together, these data suggest that ALDH1A2 and ALDH1A3 generate atRA in human cancer cells and primary tumors, but this does not appear to affect tumorigenesis or growth in immunodeficient mice." (PMID 41210994, 2025). "Meanwhile, there appears to be no transcriptomic response to ALDH1A3 inhibition in these retinoid-insensitive cancer cell lines." (PMID 41210994, 2025). "This indicates that ALDH1A3 knockout did not significantly alter the influence of SASP on cancer cell migration." (PMID 40227735, 2025).
cancer (continued). "However, the role of specific ALDH isoforms, such as ALDH1A1, ALDH1A3, ALDH2, and ALDH3A1, as CSC markers has shifted attention towards developing targeted inhibitors to prevent cancer progression." (PMID 38612911, 2024). "While the role of ALDH1A3 in the synthesis of tRA from retinaldehyde is undoubted, the RA-controlled pathways are certainly not the only ones explaining ALDH1A3 overexpression in GBM and cancer." (PMID 39001459, 2024). "We then looked at the transcript levels of these genes and found that, consistent with the protein levels, the transcription of Notch1, Sox2, and the stem cell marker Aldh1a3 genes were suppressed, while that of Numb was elevated, in response to RAB4A knockdown in RAB4A-high cancer cells." (PMID 39463384, 2024). "In contrast, no cancer progression-related changes in correlation with RARA transcriptional program was found for ALDH1A3." (PMID 38169509, 2024). "It is also clear from our analyses and the review of the literature that ALDH1A3 has multi‐factorial effects in cancer progression which is unlikely to be explained by a single gene or protein." (PMID 37753740, 2024). "Interestingly, disulfiram, a well-known treatment for alcohol abuse, has recently been suggested as a repurposed anti-cancer drug due to its inhibition of ALDH isoforms such as ALDH1A1, ALDH1A3, and ALDH2." (PMID 38612911, 2024). "Interestingly, we identified a cell subpopulation defined as cancer stem cells with a transcriptomic phenotype similar to ECCs and CA-MSCs (EPCAM, MUC1, PROM121, ALDH1A3)." (PMID 38182756, 2024). "Although not tested yet for anti-cancer activity, this rationally designed inhibitor has the highest specificity and activity among thus far reported ALDH1A3 inhibitors." (PMID 36672441, 2023). "We performed flow cytometry analysis using Ki 67 staining to examine the cancer cell proliferation with and without ALDH1A3." (PMID 36275636, 2022). "Contrastingly, Aldh1a3, Ccl5, Ccl11 and Ccl7 expression were significantly higher in ALDH+ BCSCs (P2) as compared to bulk cancer cells (P0), indicating that our sorted populations were indeed pure and RNA sequencing was reflecting the expected characteristics of these BCSC populations." (PMID 35053617, 2022). "The ALDH1A3 expression was lower in neuroendocrine and CRPC group compared with primary cancer." (PMID 32375698, 2020). "ALDH1A3 is a prominent target for chemotherapy in cancer as its inhibition disrupts NADH and ATP pools, shuts the power factory off in cancer, and sensitizes cancer cell death." (PMID 32111066, 2020). "Similarly, PKCλ and the stemness markers ALDH1A3, CD133 and OCT4 were highly expressed in HER2-enriched cancers." (PMID 32658903, 2020). "Taken together, we assume that there might be a feedback loop between ALDH1A3 and STAT3 to promote tumor progression in cancers." (PMID 32680476, 2020). "ALDH1A3, CD44, and MDR1 were found to play a role in the cancer cell resistance to FAK autophosphorylation inhibitor Y15 and their downregulation would sensitize resistant cancer cells to Y15." (PMID 31368612, 2019). "In addition, TROP2high PC3 cells showed high mRNA levels of cancer stem cell markers such as OCT4, ALDH1A3 and DCLK1." (PMID 27283984, 2016). "Of note, YAP knockdown led to a decrease in the size and number (by 2-fold) of spheres and cancer stem cell markers ALDH1A3, CD133 and Lgr5, with no change in CD44." (PMID 27527859, 2016). "Taken together, high ALDH1A3 intensity was found in non-tumorous, cancer adjacent human tissues as well as in radiosensitive tumor models, whereas radioresistant tumor models exhibited a low ALDH1A3 expression prior therapy which then increased upon treatment." (PMID 26460734, 2015). "Targeting ALDH1A3 may offer a new therapeutic strategy to enhance radiotherapy efficacy while controlling the deleterious effects of SASP, making it a promising avenue for future cancer treatments." (PMID 40227735, 2025).
cancer (continued). "We also considered the possibility that ALDH1A3 was affecting glycolysis indirectly through expression effects on master regulator of glycolytic metabolism, nuclear factor erythroid 2‐related factor 2 (NRF2), which was also shown to be modulator of the hybrid EMT/MET phenotype in cancer cells." (PMID 39251846, 2024). "However, given the nature of ALDH1 in cancer progenitor cells, we did not assess the significance of ALDH1A3 to avoid implications that would lack the certainty necessary for this analysis." (PMID 33427207, 2021). "Moreover, ALDH1A3, as a novel marker of a CSC, could predict metastasis and/or clinical prognosis in many cancers." (PMID 26575197, 2015). "Importantly, clinical data from patients with cancer that do not respond to anti-PD-1 therapy show retinol metabolism as the most enriched pathway, while other studies show that ALDH1A3 is often enriched in patients that do not respond to immune checkpoint inhibitors." (PMID 41210994, 2025). "Gene expression analyses revealed that cancer stem cell markers MMP7 and ALDH1A3 were neither transcribed before nor after PDT in CAL-33 cells." (PMID 27716314, 2016). "Cell morphology and p-MLC2 levels were assessed as amoeboid markers; ki-67 staining as a proliferative marker; WNT11, WNT5B and DAAM1 expression as non-canonical Wnt markers; and ALDH1A1, ALDH1A3, CD44, NANOG and OCT4 were evaluated as cancer stem cell-related markers." (PMID 33082334, 2020).
tumor (132 papers, 2008 to 2026). "Loss of AHR or ALDH1A3 expression eliminates the tumor development promoted by IDA both in vitro and in vivo." (PMID 40708788, 2025). "We and others have shown that high ALDH1A3 expression is associated with worse prognosis, promotes tumor growth, invasion and metastasis, and contributes to chemoresistance in multiple cancers (M.-H." (PMID 34989902, 2022). "High expression of the breast CSC gene ALDH1A3 (p = 0.030) was also associated with high tumor grade in PDS-grown MCF7 cells." (PMID 35565301, 2022). "These clinical associations highlight ALDH1A3 as a potential prognostic biomarker and as a therapeutic target preventing tumor invasion and angiogenesis." (PMID 32680476, 2020). "As tumor marker, ALDH1A3 is associated with poor outcome in a diversity of malignant tumors, amongst others also in high-grade gliomas." (PMID 33066251, 2020). "A high immunoreactivity of ALDH1A3 in tumor infiltrative area was associated with shorter OS, especially in patients with MGMT promoter methylation." (PMID 32680476, 2020). "ALDH1A3 expression is significantly correlated with poor patient prognosis and is associated with tumor progression." (PMID 31191243, 2019). "By Pearson correlation analysis in our mRNA expression microarray, mRNA expression of ALDH1A3 exhibited positive correlation with these tumor invasion associated genes." (PMID 26575197, 2015). "Both ALDH1A1 and ALDH1A3 were associated with positive HER2 status where 26% of tumours positive for either marker were HER2 positive and 11% of negative cases were HER2 positive (P < 0.0001)." (PMID 22112299, 2011). "Together, the patient tumour and cell line expression data most consistently implicated the plasminogen activation pathway could be important in ALDH1A3‐mediated invasion." (PMID 37753740, 2024). "LncRNA MIR600HG functioned as a tumor suppressor and the overexpression of MIR600HG could inhibit tumor invasion and enhance chemosensitivity by targeting ALDH1A3 (encodes an aldehyde dehydrogenase enzyme) in CRC." (PMID 36645225, 2023). "Moreover, ALDH1A3 expression levels were significantly associated with tumor size (p = 0.0228) and distant metastasis (p = 0.0315)." (PMID 32612951, 2020). "Moreover, ALDH1A3 expression was positively associated with the tumor edema grade and inversely with overall survival (OS) (median OS: 16 months vs 10 months), but with neither MGMT promoter methylation status nor Ki67 index in GBM." (PMID 32680476, 2020). "Tumor specimen analysis before treatment in this series confirmed that ALDH1A3 can significantly discriminate pro‐aggressive response in patients, showing not only association but also a linear trend of ALDH1A3 levels to pro‐aggressive response." (PMID 33151035, 2020). "Overall, our data clearly defines ALDH1A3 as a possible predictive factor of pro‐aggressiveness and could be used to predetermine tumor predisposition to acquire aggressive/invasive capacity in RCC patients treated with antiangiogenic therapies." (PMID 33151035, 2020). "The expression of ALDH1A3 is associated with tumor cell invasion." (PMID 26575197, 2015). "Knockdown of ALDH1A3 by shRNA constructs could markedly down-regulate these tumor invasion associated genes (SNAIL, SLUG and MMP2), and the abilitie of cell invasion was also reduced in vitro." (PMID 26575197, 2015). "To validate whether the expression of ALDH1A1 and ALDH1A3 genes also correlates with tumor radioresistance in PCa patients, we analyzed the expression of these genes in tumor tissues of patients with intermediate or high-risk localized PCa treated with radiotherapy (n = 67, Dresden cohort 9)." (PMID 38169509, 2024). "As a result, ALDH1A1 and ALDH1A3 may protect CSCs from antineoplastic molecules, their levels could represent a prognostic factor that could anticipate the chemotherapy efficacy and their inhibition could make the tumor cells susceptible to medical treatments." (PMID 36050388, 2022).
tumor (continued). "ALDH1A3 is the primary contributor of the Aldefluorhigh activity that defines the CSCs of multiple cancers, is associated with poor prognosis, actively promotes tumor growth, invasion, and metastasis, contributes to chemoresistance in multiple cancers, and has been proposed as a therapeutic target." (PMID 31197235, 2020). "Functionally, CLM296 impedes ALDH1A3-mediated cell invasion in vitro and, with daily dosing in vivo, significantly reduces only ALDH1A3-dependent tumor growth and lung metastasis in TNBC xenografts." (PMID 41797928, 2026). "The EGFR pathway has been identified as a main regulator of ALDH1A3 in LA, promoting tumor aggressiveness and resistance to gemcitabine." (PMID 40489465, 2025). "Through in vitro senescence and tumor growth models, we determined that ALDH1A3 knockdown accelerates the senescent-like phenotype process and that ALDH1A3 plays an important role in the induction of SASP." (PMID 40227735, 2025). "In vitro knockdown of ALDH1A3 or associated genes such as FAM3C, MCC, PMEPA1, and IRS2 reduced tumor invasion, while in vivo reduction similarly curbed tumor growth and metastasis." (PMID 40781158, 2025). "Luciferase imaging of the RARE-Luc reporter then revealed that both ALDH1A2 and ALDH1A3 synthesize atRA in tumor cells growing in vivo." (PMID 41210994, 2025). "We next aimed to identify tumor types that would respond to ALDH1A3 inhibitors in the clinical setting." (PMID 41210994, 2025). "Instead, atRA produced by ALDH1A3 acts in a paracrine fashion to activate retinoid nuclear receptor signaling in immune cells to suppress anti-tumor immunity." (PMID 41210994, 2025). "Here, we aimed to confirm the pharmacodynamic effects of MBE1 in vivo using tumor models that were previously validated to depend on ALDH1A3 for suppression of CD4 T cells." (PMID 41210994, 2025). "Tumor growth measurements demonstrated that ALDH1A3 knockout minimally reduced tumor growth in the immune compromised NSG mice compared to rescue while ALDH1A3 knockout led to a robust difference in the CD34-humanized mice." (PMID 41210994, 2025). "TAMs promote HCC malignancy by transferring the exosomal lncMMPA into tumor cells, where it acts as a microRNA sponge for miR-548s to upregulate ALDH1A3, and thereby enhancing glycolytic metabolism and tumor growth." (PMID 41361062, 2025). "ALDH1A3 not only plays a role in maintaining radiotherapy resistance but also affects tumor progression by modulating the inflammatory responses associated with senescence." (PMID 40227735, 2025). "Here, we identified ALDH1A3 as a key gene, which correlates with reduced survival and increased tumor growth." (PMID 40781158, 2025). "Our development of potent, oral, reversible ALDH1A3 inhibitors overcomes the prior undruggability of the retinoid nuclear receptor pathway and offers a distinct therapeutic approach to tumor immunotherapy and cardiovascular disease." (PMID 41210994, 2025). "Tumor tissues from patients treated with NAC showed significantly higher ALDH1A3 expression than those from treatment-naïve patients." (PMID 38669046, 2024). "This last observation suggests that contrary to fluorescein diacetate, the most common fluorescent probe used for labeling GBM during neurosurgery, the ALDH1A3 substrates can also label tumor cells contained in the brain adjacent to the tumor area." (PMID 39001459, 2024). "This showed that for the MDA-MB-468 tumors, the ALDH1A3 knockdown tumors had the greatest number of tumor-initiating cells, and 2DG treatment blocked this effect." (PMID 39251846, 2024). "For the first time, we showed that the level of ALDH1A1 is upregulated in distant metastases compared to the primary tumor sites, and the expression of ALDH1A3 has an opposite regulation." (PMID 38169509, 2024). "Regardless, the observed significant co‐expression of ALDH1A3 with tPA suggests that when ALDH1A3 is expressed in a patient tumour, tPA is most likely present." (PMID 37753740, 2024).